BATF3 (basic leucine zipper ATF-like transcription factor 3)
Diseases named in the same sentence as BATF3 in open-access papers (continued):
Sharing a sentence is not in itself a finding about the gene and the disease.
tumor (200 papers, 2013 to 2026). "VKINE, the best characterized of these proteolytes, is associated with the presence of intratumoral Batf3-DC cells and T-cell infiltration in several neoplasms, both solid and hematopoietic." (PMID 39682243, 2024). "Tumor implantation into Batf3–/– mice rescued the Mgat5-KO growth deficiency that was most pronounced at early time points." (PMID 38912584, 2024). "cDC1 depletion in Batf3-deficient mice impaired the capacity of the mice to reject transplantable immunogenic tumors and led to compromised T-cell-mediated responses to tumor immunotherapy, including ICI treatments." (PMID 36949244, 2023). "We implanted KP-HetLow tumor cells in wildtype, Rag2-/- and Batf3-/- mice, and observed a loss of tumor control in Rag2-/- and Batf3-/- mice, indicating that cDC1 are required for the induction of effective T cell responses." (PMID 37548358, 2023). "To parse the effect of Batf3−/− cDC1-deficient on the tumor microenvironment and CD39i efficacy, we performed single-cell sequencing on WT and Batf3−/− mice treated with POM-1 or PBS." (PMID 36347860, 2022). "Fractionated RT along with anti-CTLA4 produced abscopal effects caused in part by an increased number of Batf3 DCs, which were abolished in Batf3-/- mice, confirming the important role of Batf3 DCs in RT-induced anti-tumor immunity." (PMID 36532071, 2022). "Cross-presentation of tumor associated antigens by BATF3-dependent cDC1s resulted in stronger and more effective CD8+ T cell immunity." (PMID 36275666, 2022). "We next investigated if increased DC2 migration was a developmental side effect of Batf3 deficiency or if it was determined by the tumor microenvironment due to DC1 depletion." (PMID 34283809, 2021). "BATF3 DCs take in tumor-associated antigens and migrate towards the tumor-draining lymph node via the lymphatic system, where they cross-prime tumor-specific CD8+ T cells." (PMID 32854711, 2020). "Among various DC subtypes, Batf3-dependent conventional DCs (cDCs) play important roles in cross-presentation of tumor cell-associated antigens to CD8+ T cells." (PMID 33171765, 2020). "Immunotherapies such as PD1/PD-L1 blockade or CD137 agonists are ineffective in Batf3-deficient mice, highlighting the crucial role cDC1s in tumor immunity." (PMID 31143179, 2019). "The critical role of cDC1s in anti-tumor immunity has been shown using mice deficient in basic leucine zipper transcription factor ATF-like 3 (Batf3), a transcription factor required for cDC1 differentiation." (PMID 31143179, 2019). "Mounting evidence from peripheral tumors shows that Batf3-dependent cDCs are the most critical DCs in cross-presentation of tumor cell-associated antigens and priming tumor-specific T cell immunity in both mice and humans." (PMID 30683885, 2019). "We next examined the possible mechanisms underlying the crucial need for Batf3-dependent DCs in anti-tumour memory response." (PMID 28714465, 2017). "Recent studies have indicated that tumor accumulation of rare Batf3-dependent DCs bearing the CD103 marker is associated with good prognosis and immune-mediated control across mouse and human species." (PMID 26343581, 2015). "Given the role of Batf3 in Alb-Flt3L–mediated cross-presenting-DC expansion, we wanted to determine whether this pathway could also be implicated in Alb-Flt3L–mediated tumor control." (PMID 37917174, 2024). "To test whether SLC38A2 acts in a tumour-intrinsic manner or requires the immune system for its in vivo effects, we examined growth of SLC38A2-deficient MC38 tumours in Batf3–/– or Rag1–/– mice." (PMID 37407815, 2023). "While the Batf3–/– cDC1s that arose in this model were able to cross-present cell-associated antigens effectively, the mice harboring these cDC1s showed unattenuated tumor development." (PMID 34480145, 2022). "We found that BATF3 deficiency facilitated MC38 tumor growth." (PMID 31188899, 2019). "CD69 expression on tumor-associated NK cells was similar in WT and BATF3-deficient mice." (PMID 31188899, 2019).
tumor (continued). "Several oncogenic pathways have been found to influence the local antitumor immune response by modulating BATF3 DC recruitment; among them, overactivation of β-catenin pathway has been associated with a reduced recruitment of BATF3 DC into tumor, leading to failure in chemokine release." (PMID 31057613, 2019). "We thus hypothesized that recipient Batf3-deficient DCs would mediate inefficient reactivation of the transferred Tcm against the tumour." (PMID 28714465, 2017). "While ACT-DC treatment in Batf3−/− mice significantly delayed tumor growth and improved survival rates, its therapeutic efficacy was markedly reduced compared to that in the wild-type mice." (PMID 40379691, 2025). "further elucidated the importance of cross-presentation in initiating anti-tumor T cell responses, finding that BATF3-dependent dendritic cells are crucial for priming tumor-specific T cells." (PMID 40124373, 2025). "Batf3-dependent CD103+ DCs excel at cross-presenting TAAs to CD8+ T cells in tumor-draining lymph nodes, a process amplified by type I interferon (IFN-α/β) from STING activation." (PMID 40989107, 2025). "Tumor growth curves for Batf3−/− animals treated with tdRT→αPD-1 indicated that the absence of cDC1 abrogates the antitumor response, underscoring the critical role of these cells in mediating the therapeutic effects." (PMID 40675962, 2025). "Mechanistically, tumour-intrinsic WNT/β-catenin activation blocks recruitment of BATF3-lineage dendritic cells, eliminating the chemokine cues needed for priming and intra-tumour T-cell entry (a “non-T-cell-inflamed” state) across cancers." (PMID 41301037, 2025). "Within macrophages, the IFN-I produced by the STING signaling pathway can activate tumor-infiltrating Batf3(Basic Leucine Zipper Activator 3) dendritic cells and tumor antigen-specific CD8+ T cells." (PMID 41396345, 2025). "To this end, we subcutaneously implanted Mgat5-KO and control wild-type (WT) tumor cells into Batf3–/– hosts, which lack conventional type 1 DCs (cDC1s) that are specialized for CD8+ T cell activation and cross-presentation." (PMID 38912584, 2024). "In this study, we demonstrate that PU.1, IRF8 and BATF3-mediated cell fate reprogramming of tumor cells into immunogenic cDC1-like cells in situ represents a new immunotherapeutic modality for the treatment of solid tumors." (PMID 39236156, 2024). "These factors promote BATF3+, DC1s, and CD8+ T cells' anti-tumour immunity facilitated by enhanced tumour-associated antigens presenting APCs." (PMID 38698968, 2024). "(A) Tumor growth of KP-HetHigh tumor cells was implanted subcutaneously (s.c.)into Batf3-/-, Rag2-/- and WT mice." (PMID 37548358, 2023). "This superior effect was obtained upon i.v. injection of genetically engineered DCs into tumor bearing wild type mice, as well as into Batf3-/- recipients." (PMID 37623817, 2023). "BATF3-overexpressing T cells lost their exhaustion phenotype upon chronic antigen stimulation; moreover, BATF3-overexpressing CAR-T cells showed increased anti-tumor effects." (PMID 37596653, 2023). "Rather, we noticed that tumor-infiltrating CAR T cells with BATF3 OE expressed higher levels of both TCF1 and IFNγ." (PMID 37945901, 2023). "Overall, these findings demonstrate that the stimulation of tumor-specific responses in the lung by IV BCG treatment is entirely dependent on Batf3-dependent cDC1s." (PMID 37794033, 2023). "DMBA3-4 tumor rejection persisted in Batf3–/– (Batf3KO) mice and CD11c+ dendritic cell–depleted (DC-depleted) animals." (PMID 37843274, 2023). "Pilones and colleagues recently discovered that Batf3-dependent conventional dendritic cells type 1 (cDC1) are required for priming RT-induced of tumor-specific CD8+ T cells." (PMID 37152024, 2023). "We previously showed that Batf3 + Xcr1 + cDC1s are required to not only prime tumor-specific CD8 T cells in the spleen, but also maintain adoptively transferred Klrg1 + effector T cells in both spleen and tumor." (PMID 36472588, 2023).
tumor (continued). "Ectopic introduction of necrotic cells into the tumor microenvironment (TME) activates BATF3+/cDC1 as well as CD8+ leukocytes to trigger anti-tumor immune responses." (PMID 37152037, 2023). "Despite the high expression of CD155 in MC38 tumor cells, the moderate but statistically significant anti-tumor effect mediated by combination therapy was lost in the BATF3−/− mice." (PMID 35794399, 2023). "Direct injection of BATF3 DCs into the tumor region restored CXCL9 and CXCL10 expression and T-cell infiltration in WNT signaling pathway-positive tumors." (PMID 37546397, 2023). "These screens and subsequent characterization revealed that overexpressing BATF3 supports specific features of memory T cells, counters T cell exhaustion and improves tumor control." (PMID 37945901, 2023). "To investigate the contribution of CD103 + DCs toward the effects of combination therapy, we compared MC38 tumor growth upon TIGIT blockade plus RT in WT or BATF3−/− mice, which lack CD103 + CD8 + DCs." (PMID 35794399, 2023). "OVs can induce the release of tumour neoantigens and epitope spreading to promote the priming of neoantigen‐specific CD8+ T cells by BATF3+ DCs, thus inhibiting distant, uninfected tumours." (PMID 37921274, 2023). "In the tumor microenvironment, cytotoxic T cells and DCs (especially the Batf3‐dependent CD103 subtype) or inflammatory factors produced by type I IFN, IFN‐γ, and IL‐12, are closely related to tumor prognosis." (PMID 36891351, 2023). "In experimental tumor models, Batf3-competent cDC1s have been shown to be involved in the reactivation of circulating central memory T cells into antitumor resident central memory T cells, a process further promoted by anti-PD1 immunotherapy." (PMID 36949244, 2023). "Intra-tumoral injection of necroptotic cells promotes BATF3+ cDC1- and CD8+ leukocyte-dependent anti-tumor immunity accompanied by increased tumor antigen loading by tumor-associated antigen-presenting cells." (PMID 35844506, 2022). "It has been shown that basic leucine zipper transcription factor ATF-like 3 (BATF3) positive cDC1s are key factors for tumor rejection." (PMID 36275666, 2022). "Curiously, tumor-residing BATF3+ dendritic cells have been shown to be required for T cell trafficking that can ultimately participate in the recruitment of TVM cells to tumors due to high avidity of TVM cells for IL-15." (PMID 36330506, 2022). "αCD40-induced monocyte/macrophage priming generates atypical tumor-specific T cells that lack antitumor activity in Batf3–/– mice." (PMID 35393950, 2022). "As expected, a significant decline in the number of CD11c+ DCs, particularly CD103+CD11c+ and CD8α+CD11c+ DCs, was observed in tumor-infiltrating lymphocytes of DEXP&A2&N-treated Batf3−/− compared to wild-type mice." (PMID 35488312, 2022). "Unexpectedly, depletion of monocytes by clodronate liposomes significantly decreased tumor size following αCD40 in Batf3–/– mice." (PMID 35393950, 2022). "The BATF3 transcription factor plays an important role in anti-tumor immune responses and impacts cancer immunotherapies, such as immune-checkpoint blockade and adoptive transfer T cell therapy." (PMID 35759090, 2022). "The link between increased RT-mediated immunogenicity and synergy with ICIs was recently shown to depend on the RT-mediated stimulation of tumor cells to produce IFN-β, a necessary prerequisite for Batf3-lineage DC activation and recruitment to the tumor site." (PMID 35681654, 2022). "Injecting a virus-based vector expressing XCL1 and soluble Flt3L intratumorally improved tumor control in MC38- and B16-bearing mice through the accumulation of cross-presenting Batf3 DCs in the tumor draining lymph node." (PMID 35626062, 2022). "The treatment increased the infiltration of CD8+ T cells and facilitated the anti-tumour activity of BATF3-dependent cDC1 in tumour-bearing mice." (PMID 36140243, 2022).
tumor (continued). "Supplementation of Flt3L significantly amplified CD103+CD11c+ DCs and led to higher percentages of tumor-free rates in HCC mice, further underlining the importance of functional host Batf3-dependent DCs in driving DEX-mediated antitumor responses." (PMID 35488312, 2022). "Tumor models were constructed by subcutaneous injection of MB49 cells into Batf3−/− or Batf3+/+ (WT) C57BL/6 J mice, and then treated with POM-1 or PBS, respectively." (PMID 36347860, 2022). "In the current study, we have found that both Batf3 is an important factor for the ability of Alb-IFNβ to control tumor progression." (PMID 35459734, 2022). "Whereas, Batf3 DCs can be recruited to the tumor bed through the chemokine (C-C motif) ligand 5 (CCL5) and XCL1 (also known as ATAC, lymphotactin, or SCM-1) produced by NK cells." (PMID 35626062, 2022). "In other words, it plays important role in cross-presentation in tumor rejection and deletion of the transcription factor Batf3 ablated development of CD8alpha + dendritic cells." (PMID 35410350, 2022). "Next, splenocytes from Thy1.1+ Teffs were isolated 7 days after vaccination and transferred into day 3 tumor-bearing Batf3+/+ or Batf3–/– mice." (PMID 35393950, 2022). "Future immunotherapy agents are likely to synergize with well-established antibodies for checkpoint blockade by enhancing infiltration with crucial immune cells such as activated Batf3 DCs and tumor-antigen-specific CD8+ T cells." (PMID 35626062, 2022). "Further, CD40 agonist promoted the priming of tumor-specific CD8+ T cells in Batf3–/– mice, which occurs via monocytes/macrophages." (PMID 35393950, 2022). "In particular, Batf3-lienage DCs (basic leucine zipper transcription factor ATF-like 3 expressing dendritic cells) are required for successful cross-priming of effector T cells in the tumor draining lymph node." (PMID 35626062, 2022). "Gitr+CD8+ T cells isolated from both spleen and tumor of αCD40-treated Batf3–/– mice exhibited higher levels of proinflammatory markers, including IFN-γ and TNF-α." (PMID 35393950, 2022). "Both tumor and spleen size were significantly larger in Batf3–/– than Batf3+/+ mice at day 14 posttumor." (PMID 35393950, 2022). "To circumvent this issue, we performed adoptive transfers of effector or memory Batf3+/+ tumor-specific T cells into tumor-bearing Batf3+/+ or Batf3–/– hosts." (PMID 35393950, 2022). "Transferred Teffs and memory T cells exhibited greater tumor control in Batf3+/+ mice compared with Batf3–/– mice." (PMID 35393950, 2022). "Batf3 KO mice treated with Alb-IFNβ and E7 vaccination apparently reduced their ability to control the tumor progression and generated fewer E7-specific CD8 +T cells." (PMID 35459734, 2022). "Ectopic introduction of necroptotic cells to the tumor microenvironment promotes BATF3+CDC1− and CD8+ leukocyte-dependent antitumor immunity accompanied by increased tumor antigen loaded by tumor-associated antigen-presenting cells." (PMID 39872161, 2022). "We found that treatment of tumor-bearing Batf3−/− mice with mito + oHSV + ICI was ineffective in controlling tumor growth or prolonging survival." (PMID 35163675, 2022). "Accordingly, BATF3-deficient mice that lack cDC1 cells have impaired virus-specific cytotoxic T lymphocyte (CTL) responses and ineffective tumor rejection." (PMID 35720410, 2022). "We selected early time points for the T cell transfer to minimize differences in tumor size that occur in Batf3+/+ and Batf3–/– mice." (PMID 35393950, 2022). "The results indicated that silencing of SETDB1 limited tumor cell proliferation and the infiltration of tumor cells by T cells via FOSB/miR-22/BATF3/PD-L1 axis and consequently arresting tumor cell immune evasion." (PMID 35497876, 2022). "They express checkpoint molecules such as LAG3 but also secrete CCL4 and CXCL13 and thereby attract more Batf3 DCs and B cells into the tumor microenvironment." (PMID 35626062, 2022).
tumor (continued). "BATF3 DCs have the ability to cross-present tumor-derived antigens through the MHC-I pathway and thus initiate T cells." (PMID 33859752, 2021). "The T cell inflamed tumor biomarker CD274 (PD-L1) was significantly upregulated in the LsS4D in addition to BATF3, CD247 (CD3ζ), CD80 among others." (PMID 33776991, 2021). "Direct injection of BATF3 DCs helped restore T-cell infiltration in β-catenin-positive tumors and resulted in modest tumor suppression." (PMID 33859752, 2021). "Tumor-derived FLT3L increased the infiltration of BATF3 DCs and CD8+ T lymphocytes in mouse tumors and enhanced migratory and resident DC subsets in draining lymph nodes (DLNs), suggesting a mobilizing effect of FLT3L on DC cells." (PMID 33859752, 2021). "Altogether, the effects in Batf3–/– mice highlight that cDC1s are negatively affected by OE of Mmp2 and, in their absence, tumor growth in response to Mmp2 OE is compromised." (PMID 34032639, 2021). "The effector cells responsible for improved tumor control in Batf3–/– mice were unclear and needed further investigation." (PMID 34283809, 2021). "IFN regulatory factor 8 (Irf8) and basic leucine zipper transcriptional factor ATF-like 3 (Batf3) are critical transcriptional factors in the development of cDC1s and are essential for tumor rejection." (PMID 34262904, 2021). "This outcome suggests that WNT/β-catenin signaling activation and defective BATF3 DC recruitment mediate T-cell exclusion and tumor cell escape from the immune system." (PMID 33859752, 2021). "Later on, the same group has shown that repeated medium-high doses, below a threshold of 10-12 Gy, do not induce DNA exonuclease Trex1, and thus elevates interferon-β production in tumor cells, which promotes recruitment and activation of Batf3-dependent DCs." (PMID 34177901, 2021). "Most importantly, containment of tumor growth was reduced in Timd4−/−:Batf3−/− chimeras as shown by more abundant lesions and larger nodules than in animals reconstituted with wild-type:Batf3−/− bone marrows." (PMID 33854047, 2021). "Anti-PD-L1 antibody treatment delays melanoma tumour growth in this model but, despite PD-L1 expression in tumour cells, the anti-tumour effect of PD-L1 blockade was reduced in Batf3−/− mice which lack CD103+ DCs." (PMID 34141724, 2021). "As a functional outcome of enhanced DC2 migration, CD4+ T cell activation was significantly augmented in the dLN and tumor of Batf3–/– mice." (PMID 34283809, 2021). "The combined immunotherapy-ablation protocol further upregulated T cell activation markers such as Gzma, Gzmb, and Batf3 in the directly-treated tumor compared to ablation alone." (PMID 33441763, 2021). "DC1 depletion dramatically attenuated tumor growth, with Batf3–/– mice displaying an 80% reduction in tumor size at 3 weeks after implantation." (PMID 34283809, 2021). "The combination-mediated induction of an endogenous tumor-specific response was completely abolished in Batf3-KO mice." (PMID 34810235, 2021). "On the other hand, attenuated VV activates STING and Batf3 pathways in DCs and subsequently induce potent anti-tumor immunity." (PMID 31969562, 2020). "Specifically, tumor cell-intrinsic β-catenin activation prevents host anti-tumor immune response by failure to recruit Batf3-leneage DCs, which are involved in both the priming phase and the effector phase of anti-tumor immune response." (PMID 32894202, 2020). "Cross-presentation of tumor antigen by cDC1s that express the transcription factor Batf3 induce priming of rare naïve tumor-reactive T cells." (PMID 33584701, 2020). "Batf3-DCs in the tumor microenvironment (TME) are also necessary at the time of anti-PD-L1 therapeutic effect." (PMID 32894202, 2020). "A critical process in T cell priming against tumor antigens involves the recruitment and activation of Batf3-lineage dendritic cells (DCs) expressing CD103 in the mouse." (PMID 33171765, 2020).